SMURF1 (SMAD specific E3 ubiquitin protein ligase 1)
Diseases named in the same sentence as SMURF1 in open-access papers (continued):
Sharing a sentence is not in itself a finding about the gene and the disease.
cancer (39 papers, 2011 to 2025). A tumor composed of atypical neoplastic, often pleomorphic cells that invade other tissues. "We further addressed the consequences of SMURF1 depletion in ER alpha signaling, which linked to ER alpha positive cancer proliferation." (PMID 29433542, 2018). "Smurf1 has also been implicated in tumor development by ubiquitination of cancer-suppressing proteins, in cancer metastasis by suppression of epithelial-mesenchymal cell transition (EMT) pathway, in pancreatic cancer invasiveness, cardiovascular diseases, and in liver steatosis." (PMID 37228615, 2023). "The role of SMURF1 has been implicated in a variety of cancers." (PMID 33418880, 2021). "Smurf1 has also been implicated in cancer cell proliferation, migration and invasion." (PMID 30116722, 2018). "In addition, the expression levels of Smurf1 were found to be elevated both in ccRCC cell lines and cancer tissues, and associated with worse patient survival." (PMID 30116722, 2018). "Oncogenic E3 ligase SMAD Specific E3 Ubiquitin Protein Ligase 1 (Smurf1) is highly expressed in cancer cells and recognized as a new mediator of selective autophagy by interacting with the nascent autophagosome membrane." (PMID 36810259, 2023). "Smurf1 and Smurf2 are considered to act as both promoters and suppressors under different conditions through regulating certain targets involved in cancer progression." (PMID 37537194, 2023). "SMURF1 levels were noted to be downregulated in the tumors derived from SNHG3-silenced cancer cells." (PMID 37568787, 2023). "Neddylation increases the ubiquitin ligase activity of SMURF1, which promotes cancer cell proliferation, invasion, and increases tumor volume in a mice xenograft model." (PMID 37717015, 2023). "Existing studies reported an inhibitory role of Smurf1 in cancer metastasis in lung cancer by targeting SRSF5." (PMID 36291166, 2022). "Smurf1 supports breast cancer growth through facilitating estrogen receptor α signaling, which is necessary for estrogen‐dependent cancer progression." (PMID 34614303, 2022). "Meanwhile, the activity of Smurf1 in mediating RhoA degradation is critical for cancer cell invasive activity." (PMID 35654587, 2022). "By contrast, in aggressive stages of cancer, for example, in triple negative breast cancer, the SMURF1 level was shown to neutralize the SMURF2 inhibitory effect of tumorigenesis." (PMID 33418880, 2021). "Knock down of SMURF1 reduces tumorigenesis in a variety of cancer cell models such as of pancreatic, prostate, and ovarian cancer." (PMID 33418880, 2021). "Other protein kinases, such as checkpoint kinase (Chk1) and Interleukin-1 Receptor Associated Kinase 2 (IRAK2), can reduce protein levels of phosphorylated Smurf1 at Thr145, Thr161, and Thr682 compared to its basic expression in cancers." (PMID 33718111, 2020). "In some cancers, Smurf1 is phosphorylated at specific threonine residues by cAMP/PKA, which modulates Smurf1 ubiquitin ligase activity or mediates its unconventional ubiquitination of substrates." (PMID 33718111, 2020). "In sum, Smurf1 and Smurf2 are key proteins in the regulation of cancer metastasis, albeit further investigations are required to further elucidate their opposite roles in cell migration and invasion." (PMID 33114139, 2020). "The mechanism by which SMURF1 leads to poor cancer prognosis requires further research." (PMID 40342823, 2025). "SMURF1 plays crucial roles in bone homeostasis, cell polarity, and cancer progression." (PMID 39941157, 2025). "Therefore, our study expands our understanding on functions of Smurf1 and Smurf2 in cancer progression, highlights the role of the Smurf1- and Smurf2-RNF220 axes during Shh-MB progression, and provides new potential targets for Shh-MB treatment." (PMID 37537194, 2023). "Moreover, the protecting role of SMURF1 for cancer cell survival was also impaired with the NRF2 depletion in LN229 cells." (PMID 37316499, 2023).
cancer (continued). "Thus, Smurf1 plays important roles in cancer progression in different ways depending on different context." (PMID 35654587, 2022). "The suppression of Smurf1 inhibits the progression of multiple types of cancer." (PMID 34614303, 2022). "Although numerous reports implicate the involvement of SMURF1 in cancer progression, very few cases could be explained by its regulation of TGFβ signaling events." (PMID 33418880, 2021). "Like SMURF1, SMURF2 is also associated with different types of human cancers." (PMID 33418880, 2021). "SMURF1‐mediated RhoA degradation is vital for cancer cell metastasis." (PMID 33377649, 2020). "SMURF1 is widely identified as an oncogene in various cancers." (PMID 32248648, 2020). "Due to RhoB promoting apoptosis in various cancer cells, this finding illustrates that in some cancers, Smurf1 might act as an oncoprotein to degrade RhoB and facilitate tumorigenesis." (PMID 33718111, 2020). "The pro-oncogenic role of Smurf1 was also noted in other types of cancer." (PMID 30116722, 2018). "While our data are the first to implicate SMURF1 in the regulation of a CSC-like population, SMURF1 may play a similar role in other cancers." (PMID 25471937, 2014). "To understand whether LATS1 stability is also regulated by other members of the NEDD4-like family of E3 ligases, we selected 4 ubiquitin ligases including NEDD4, WWP1, Smurf1 and Smurf2 that have been shown to be involved in the development of human cancers." (PMID 23573293, 2013). "In addition, SMURF1 is necessary for cancer stem cell maintenance in HNSCC." (PMID 33418880, 2021). "This polypeptide promotes cancer growth by inhibiting the binding between serine/threonine kinase 38 (STK38) and SMAD-specific E3 ubiquitin protein ligase 1 (SMURF1), which prevents MEKK2 from undergoing ubiquitination and proteasomal degradation." (PMID 38835343, 2024). "The miR-497 mediated targeting of SMURF1 led to a reduction in the migration and invasion of SKOV-3 and OVCAR-3 cancer cells." (PMID 37568787, 2023). "Elevated expression of NEDD8, SMURF1, NAE1, and UBE2M have been found to correlate with cancer development and poor prognosis." (PMID 37717015, 2023). "In ovarian cancer, aberrantly activated Smurf1‐mediated degradation of tumor suppressor ARHGAP26 promotes invasion and metastasis of cancer cells through the β‐catenin pathway." (PMID 34614303, 2022). "GLI3, SMURF1, RBPJL, JAG1, LFNG and DTX2 were some of the most amplified genes present in at least 18 cancers." (PMID 31523055, 2019). "In this review, we highlighted and discussed the cancer related biological functions of two C2-WW-HECT E3 ligases, Smurf1 and Smurf2." (PMID 30116722, 2018). "Various studies have reported that miR‐503 can target SMURF1 and SMURF2 (SMAD ubiquitination regulation factors 1 and 2), thereby enhancing TGF‐β (transforming growth factor beta) signaling in individual biological processes other than cancer." (PMID 37212485, 2023). "Considering the elevated expression of SMURF1, SMURF2, NEDD4-2 in different cancers (Section 7.1 and Section 7.3), similar inhibitors of SMURF2 and NEDD4-2 could be identified." (PMID 33418880, 2021). "Previous studies revealed that Smurf1 as a cancer-related gene could promote EMT and positively regulate the PI3K/AKT signaling pathway, which influenced cancer cell proliferation, migration, and invasion." (PMID 30631050, 2019).
cancer (continued). "Although this study is not the first one to explore the implication of miR‐125a in cancers, we provided the evidence that Smurf1 was one potential target of miR‐125a in CRC, which is some novel finding in this study." (PMID 31141316, 2019). "In this study, we characterize a novel non-genomic regulatory mechanism that SMURF1 controls ER alpha ubiquitination and stability, which subsequently regulates estrogen-dependent gene expression and cancer cell proliferation." (PMID 29433542, 2018). "Thus identifying mechanisms to modulate the Smurf1 E3 ligase activity could provide a novel therapeutic avenue for cancer by targeting both early phases of tumorigenesis and later stages of metastasis, thereby attacking cancer in two phases and enhancing cancer patient survival." (PMID 27036023, 2016). "Although the noncovalent binding region in Smurf1 takes a role in the promotion of cell migration, whether there is a link between neddylation of Smurf1 and cancer cell migration is unknown." (PMID 33718111, 2020).
infection (5 papers, 2018 to 2024). The state of being infected such as from the introduction of a foreign agent such as serum, vaccine, antigenic substance or organism. "We observed that 45% of wild-type mice inoculated with the high-dose inoculum of MHV-A59 succumbed between day 6 and 7 post-infection, while all Smurf1−/− mice succumbed between day 2 and 6 post-infection." (PMID 39452742, 2024). "Smurf1−/− BMDMs secreted similar levels of IL-6 compared to MHV-A59-infected wild-type in all periods evaluated, with the exception of 48 h post-infection, when IL-6 secretion by Smurf1−/− BMDMs was lower, compared to wild-type infected cells." (PMID 39452742, 2024). "Our in vivo data show that at day 2 post-infection, both wild-type and Smurf1−/− mice exhibited similar viral titers in the lungs." (PMID 39452742, 2024). "We observed that Smurf1 mRNA is upregulated in the lungs of wild-type mice upon infection with MHV-A59." (PMID 39452742, 2024). "Overall, our findings suggest that Smurf1 is essential for host resistance against Betacoronavirus infection and modulates the systemic inflammatory response triggered by the infection." (PMID 39452742, 2024). "The analysis of G/L in infected mice showed a significant increase in both wild-type and Smurf1−/− mice on day 2 post-infection compared to their respective mock groups." (PMID 39452742, 2024). "In the next sections, we will summarize major substrates and processes related to immune responses and host resistance to infection that are directly regulated by Smurf1." (PMID 37228615, 2023). "However, by day 5, the virus was detectable only in the lungs of Smurf1−/− mice, which suggest that MHV-A59 is cleared from the lungs of wild-type mice after 48 h post-infection possibly through mechanisms mediated by Smurf1." (PMID 39452742, 2024). "However, MHV-A59 stimulated the production of CXCL1 in Smurf1−/− BMDMs as early as 12 h post-infection compared to uninfected Smurf1−/− or MHV-A59-infected wild-type BMDMs." (PMID 39452742, 2024). "It suggests that an increased Smurf1-dependent inhibition of antiviral signaling is a mechanism that could be exploited by viruses to establish infection." (PMID 37228615, 2023). "It was recently shown that the negative regulation of MyD88 by Smurf1 may be exploited by pathogens to facilitate the establishment of infection." (PMID 37228615, 2023). "SMURF1 and SMURF2 transcripts were detectable prior to infection and showed moderate induction during DENV2 infection, although SMURF1 expression dropped to near constitutive levels by 48 h." (PMID 32117091, 2020). "Our data showed that the absence of Smurf1 did not interfere with viral cell attachment and entry, as the viral title was similar between wild-type and Smurf1−/− BMDMs at time zero of infection." (PMID 39452742, 2024). "Using a murine model of infection with MHV-A59, we found that mice lacking Smurf1 were more susceptible to intranasal coronavirus inoculation." (PMID 39452742, 2024). "Here, we also observed substantial increases in the mRNA expression of different HECT E3 ligases, specifically WWP1, WWP2, SMURF1 and NEDD4, in infected Vero E6 and Calu-3a cells, which could exacerbate infection." (PMID 36754974, 2023). "Like SIAH1, miR-424 inhibited expression of SMURF1 and SMURF2 during DENV2 infection." (PMID 32117091, 2020). "As to Smurf1 mRNA, VSV infection did not significantly affect the level of Smurf1 mRNA in HT1080 and 2fTGH cells within 6 hours after infection." (PMID 29734366, 2018).
cardiovascular diseases (2 papers, 2022 to 2023). "Smurf1 is implicated in cardiovascular diseases through substrate ubiquitination." (PMID 35034538, 2022). "More importantly, recent data suggest that Smurf1 is associated with cardiovascular diseases." (PMID 35034538, 2022).
heart diseases (1 paper, 2020). "Among the nine members of the NEDD4 family, NEDD4-1, NEDD4L, ITCH, WWP1, WWP2, SMURF1 and SMURF2 are involved in heart diseases." (PMID 33110392, 2020).
neurodevelopmental disorder (1 paper, 2024). A behavioral and cognitive disorder with onset during the developmental period that involves impaired or aberrant development of intellectual, motor, or social functions. "Also, we have identified 15 de novo variants in genes that were previously implicated in ASD or related neurodevelopmental disorders (PHF21A, WASF1, TCF20, DEAF1, MED13, CREBBP, KDM6B,SMURF1, ADNP, CACNA1G, MYT1L, KIF13B, GRIA2, CHM, and KCNK9)." (PMID 38572415, 2024).
transplant kidney (1 paper, 2019). "Depending on these reported findings, we hypothesized that Smurf1 might play a critical role in the transplant kidney interstitial fibrosis caused by EMT." (PMID 31140729, 2019).
SMURF1 also shares sentences with these, for which no sentence is quoted: atherosclerosis (3 papers); bladder cancer (2); cervical cancer (2); chronic kidney disease (2); neuroblastoma (2); pulmonary hypertension (2); acute myeloid leukemia (1); Autoimmunity (1); benign skin tumors (1); bone disorder (1); brain diseases (1); cerebral atherosclerosis (1); chronic lung disease (1); coronary atherosclerosis (1); fibrosis (1); Hyperglycemia (1); idiopathic pulmonary arterial hypertension (1); Intellectual disability (1); macular degeneration (1); malignant glioma (1); medulloblastoma (1); metabolic disorders (1); Obesity (1); osteonecrosis of the femoral head (1); Pulmonic stenosis (1); renal cell carcinoma (1); sarcoidosis (1); Stroke (1); tuberculous meningitis (1); valvular heart diseases (1).
A further 1 disease shares a sentence with SMURF1 in 1 paper.